CRP (C-reactive protein)
Diseases named in the same sentence as CRP in open-access papers (continued):
Sharing a sentence is not in itself a finding about the gene and the disease.
COVID-19 (continued). "Firstly, severe COVID-19 is associated with a systemic hyper-inflammation state with increased cytokine levels and highly elevated C-reactive protein (CRP) all of which are known to impact drug PK through the downregulation of CYP isoenzymes." (PMID 35153785, 2022). "In contrast to other biomarkers, such as IL-6, CRP, D-dimers, and ferritin, suPAR increases earlier in COVID-19 patients, reflecting a higher risk of disease progression to respiratory failure and respiratory failure mortality." (PMID 36038915, 2022). "Components of the AIFELL score that are associated with severe stages of COVID-19 in the scientific literature are consolidative infiltrates as a sign of pulmonary involvement, fever and elevated CRP levels as a result of a systemic inflammatory process." (PMID 35328157, 2022). "COVID-19 symptoms rapidly become critical 7–10 days after onset, which is associated with an increase in acute-phase response markers, including CRP and ferritin, and inflammatory cytokines, including IL-6, IL-2, and TNF-α." (PMID 34436742, 2022). "Anti-inflammatory drugs are administered to curb the hyper-inflammatory state associated with increased C-reactive protein, pro-inflammatory cytokines, and chemokines in severe COVID-19 patients." (PMID 35381033, 2022). "In the same study, lower levels of 25(OH)D were associated with higher levels of ferritin, D-dimer, and CRP, which are inflammatory markers that are commonly elevated in patients with COVID-19." (PMID 35276822, 2022). "Factors significantly associated with nausea persistence in COVID-19 were female sex, high body mass index, the presence of dyspnea, and increased C-reactive protein levels." (PMID 34751672, 2022). "Lymphocytopenia, neutrophilia, low platelets, low hemoglobin, and high levels of AST, ALT, blood urea, CRP, and D-dimer were linked to severe to critical COVID-19 group (P value < .05)." (PMID 35230875, 2022). "Along with high C-reactive protein, fibrinogen and soluble uPAR serum levels turned out to be independently associated with more severe lung damage in COVID-19 patients." (PMID 36555850, 2022). "Anemia was the strongest predictor in association with COVID-19 (β = 3.65, CI = 1.46–5.39, p-value < 0.001), followed by elevated CRP (β = 2.11, CI = 1.20–3.06, p-value < 0.001), and respectively IL-6 (β = 1.92, CI = 1.20–2.47, p-value = 0.001)." (PMID 36579593, 2022). "Regarding laboratory tests on admission, compared to non-IS patients, the IS group had higher average levels of inflammatory markers (D-dimer and C-reactive protein); these markers have been associated with a worse prognosis of COVID-19." (PMID 34343222, 2021). "Lymphopenia, thrombocytopenia, and elevated levels of interleukin-6, ferritin, D-dimer, aspartate aminotransferase, C-Reactive-Protein, procalcitonin, creatinine, neutrophils and leucocytes were associated with severe and fatal COVID-19 cases." (PMID 34185801, 2021). "There is a possibility that pro-inflammatory neutrophils and C-reactive protein induce “cytokine storm” related to endothelialitis caused by COVID-19 infected cancer patients." (PMID 34094950, 2021). "Renal impairment, plasma CRP concentration and blood platelet count have been previously reported to be associated with a poorer prognosis in patients with COVID-19 and we here confirm their independent associations in a Machine Learning model." (PMID 34795637, 2021). "Other biomarkers, such as cardiac troponin, C-reactive protein, ferritin, fibrinogen, prothrombin time, and D-dimer were shown to be associated with a higher risk of mortality among critically ill COVID-19 patients in our study." (PMID 33930079, 2021). "We focused the laboratory analysis on C-reactive protein (CRP), ferritin, fibrinogen, procalcitonin, D-dimer, and creatinine based on their reported associations with severe COVID-19." (PMID 34533459, 2021).
COVID-19 (continued). "PNI scores showed an independent and inverse association with COVID-19 severity (OR: 0.797; p = 0.030), after adjusting for confounding factors such as demographics, indexes for liver and renal functionality, C-reactive protein levels, and smoking habits." (PMID 33801645, 2021). "As in previous studies, we found that age, inflammatory markers (specifically, ferritinemia and CRP), and lung involvement were associated with severe COVID-19 in our study sample." (PMID 34284784, 2021). "High CRP levels have reportedly been associated with severity and progression to pneumonia in COVID-19 patients." (PMID 34888326, 2021). "Age, male sex, functional dependency, pneumonia, heart failure and elevated CRP levels were also found to be associated with mortality risk, thus collaborating data from other studies of older patients with COVID-19." (PMID 33789578, 2021). "It has been revealed that eosinophilia in patients with COVID-19 associated with lower level of CRP, lower requirement for hospitalization and ICU admission." (PMID 34952570, 2021). "Amongst patients with diabetes presenting with COVID-19 in the hospital setting, CRP and age are useful markers associated with an increased risk of death within the first week of admission, specifically amongst the most deprived regions in the community." (PMID 35095757, 2021). "In this study, we have identified nine factors, including age, dyspnea, anorexia, WBC, NLR, PLT, AST, ALB, and CRP, that were the independent risk factors for COVID-19 fatality." (PMID 34733858, 2021). "Male sex, Asian ethnicity, haematological cancer, ≥24 months since cancer diagnosis, fever, dyspnoea, highest range ferritin and CRP were all associated with an increased risk of severe infection and COVID-19-specific death in cancer patients." (PMID 34400804, 2021). "CRP is a good inflammatory marker revealing the association between diabetes and adverse COVID-19 outcomes, including the need for ICU admission, dyspnea, and length of stay, whereas fibrinogen for coagulation dysfunction." (PMID 35095801, 2021). "It was found in this report, which assessed increased CRP levels at admission for COVID-19 patients with high mortality risk." (PMID 34786318, 2021). "Multiple clinically established biomarkers, such as LDH, ferritin, CRP, and D-dimer, are currently being evaluated to assess the risk of clinical deterioration from a COVID-19 diagnosis." (PMID 33444289, 2021). "Eight clinical markers of lactate dehydrogenase, C-reactive protein, albumin, comorbidity, electrolyte disturbance, coagulation function, eosinophil and lymphocyte counts were associated with the severity of COVID-19." (PMID 34372792, 2021). "Symptomatic COVID-19 patients were characterized by blood eosinophilia which was associated with lower C-reactive protein (CRP) and better disease outcome, indicating a protective role for eosinophils in the first stages of COVID-19." (PMID 34209213, 2021). "In severe COVID-19 patients, a systemic pro-inflammatory signature, including elevated plasma IL-6 and C-reactive protein (CRP) levels, was associated with clinical worsening and 2-month mortality." (PMID 33573221, 2021). "A positive association between CRP concentrations and lung lesions was reported in COVID-19 patients." (PMID 36168478, 2021). "It is generally known that cytokine storm was associated with the process and the levels of IL-6 and CRP can predict the severity and prognosis of COVID-19 patients." (PMID 33557785, 2021). "First, it should be acknowledged that other laboratory parameters (e.g., LDH, lymphocytes, creatinine, C-reactive protein) have been associated with severity and mortality of COVID-19." (PMID 34572414, 2021). "This was corroborated by a retrospective cohort study where COVID-19 patients with vitamin D deficiency had significantly lower haemoglobin and lymphocyte counts and higher levels of inflammatory markers, including C-reactive protein." (PMID 34638897, 2021).
COVID-19 (continued). "As a systemic inflammatory marker, C-reactive protein (CRP) was associated with disease development and showed good performance in predicting severity in an early stage of COVID-19." (PMID 34067072, 2021). "Accordingly, it has been documented that the risk of developing severe events in COVID-19 patients is increased by about 5% for every one-unit increase in CRP levels." (PMID 34300279, 2021). "Obesity, diabetes, oxygen saturation, lung involvement on computed tomography examination, the C-reactive protein level, levels of 15 cytokines, and lymphopenia on admission were associated with progression to severe COVID-19." (PMID 34386533, 2021). "This is in keeping with other whole observational studies and metanalyses, which have identified that advanced age and CRP predisposes COVID-19 patients to a higher risk of ventilator support and death in people with or without diabetes." (PMID 35095757, 2021). "The initial model for the prediction of the risk of progression of COVID-19 included diabetes, obesity, hypoxemia, lung involvement on CT, the CRP level, the lymphocyte count, and levels of 15 cytokines." (PMID 34386533, 2021). "In conclusion, our results demonstrated that SpO2, D-dimer levels, and the CRP/Alb ratio on admission were independent risk factors for progression to critical disease or death in patients with severe COVID-19." (PMID 34900028, 2021). "The combined use of laboratory parameters with inflammatory markers increases the ability to identify COVID-19 patients at a higher mortality risk, as with serum albumin, C-reactive protein (CRP), and neutrophilia." (PMID 34683480, 2021). "Our findings provided an important piece of evidence that both elevated CRP and decreased albumin were independently associated with hospital long-stay in patients with moderate COVID-19." (PMID 33853568, 2021). "C-reactive protein is associated with overproduction of inflammatory cytokines in patients, which is linked with the degree of severity and mortality of patients with COVID-19." (PMID 33946171, 2021). "A number of recent studies have demonstrated that CRP and D-dimer levels are associated with the severity of COVID-19 symptoms and prolonged hospital stay." (PMID 34300252, 2021). "The immune/inflammatory markers — lymphocytes (%), neutrophils (%), and high-sensitivity C-reactive protein (hs-CRP, mg/l) — were significantly associated with the overall survival (OS) of COVID-19 patients in dose-dependent manners." (PMID 34777350, 2021). "Decreasing leucocytes and eosinophils as well as increasing hemoglobin and CRP were associated with an increased likelihood of being COVID-19 positive tested." (PMID 33931692, 2021). "In conclusion we found that, irrespective of potential confounders including albuminemia, elevated CRP levels measured in the early stages of COVID-19 were associated with lower 14-day survival among hospitalized geriatric patients." (PMID 34506514, 2021). "Laboratory tests are a promising source of objective data, and there is evidence that inflammatory markers (e.g., C-reactive protein) and markers of cardiac, liver, and renal dysfunction are associated with severe COVID-19." (PMID 34123422, 2021). "The magnitude of senescence led to a high surge of IL6, IL1b, IFNγ, C-reactive protein, and TNFα is reported in several epidemiological studies to lower airway and lung injury and risk for in COVID-19 elderly patients." (PMID 33815889, 2021). "Age, systolic blood pressures of less than 120 mmHg, elevated CRP and potassium values and/or the presence of atrial fibrillation at baseline identify COVID-19 patients at high risk for cardiovascular events and death." (PMID 34501427, 2021). "A high CRP/Alb ratio on admission was associated with disease severity, clinical progression, and poor prognosis of COVID-19." (PMID 34900028, 2021). "We identified age, dyspnea, anorexia, NLR, PLT, AST, ALB, and CRP as independent risk factors associated with in-hospital mortality of COVID-19." (PMID 34733858, 2021).
COVID-19 (continued). "This inflammatory process is a risk factor for AKI, and other reports have identified C-reactive protein levels and altered white blood cell count as predictors of COVID-19 severity in patients with kidney function impairment." (PMID 34033655, 2021). "But only CRP and ferritin showed good predicting performances for COVID-19 severity based on the diagnostic performance evaluation by ROC analysis." (PMID 34314447, 2021). "How CRP is associated with decreased survival in older adults with COVID-19 is not yet fully understood." (PMID 34506514, 2021). "In our adjusted analyses, we observed that thrombosis is not only an important contributing factor to the pathogenesis of COVID-19 but also inflammation, which plays an important role, with both CRP and ferritin levels being associated with worse outcomes." (PMID 34909913, 2021). "A recent study identified that old age, comorbidities and CRP were risk factors of cardiac injury in patients with severe COVID-19 by multivariate regression analysis." (PMID 33627696, 2021). "When looking at laboratory results, CRP levels in the highest tertile (146–528 mg/L) were also associated with an increased risk of an early death due to COVID-19 (HR: 12.70, 95% CI: 1.58–102.40) when compared to patients with CRP levels in the lowest tertile." (PMID 34400804, 2021). "Of mention, the cytokine storm, observed in the course of COVID-19, is associated with induction of CRP gene over-expression in later disease stages." (PMID 34573989, 2021). "A number of studies have shown an association between elevated CRP and higher rates of COVID-19-related hospitalization and mortality." (PMID 34441038, 2021). "Elevated plasma CRP levels are associated with disease severity in patients with COVID-19, and higher CRP levels correlated with longer durations of hospitalization." (PMID 34757529, 2021). "Increased CRP levels are also associated with worse symptoms and worse organ injury among COVID-19 patients." (PMID 34336871, 2021). "Again, ferritin in the highest tertile (HR: 16.11, 95% CI: 3.81–68.17) and highest two tertiles for CRP (HR: 2.88, 95% CI: 11.13–7.31 and HR: 4.10, 95% CI: 1.66–10.10) were at an increased risk of COVID-19 death compared to the lowest tertiles comparators." (PMID 34400804, 2021). "High C-reactive protein independently predicted the risk of mortality in a cohort of 183 COVID-19 patients." (PMID 33693030, 2021). "Similar findings were found in this study where increased CRP rates were measured at admission for the high mortality risk COVID-19 patients." (PMID 33897907, 2021). "Lymphopenia, thrombocytopenia and higher levels of IL-6, ferritin, D-dimer, aspartate aminotransferase, lactate dehydrogenase, CRP, procalcitonin, creatinine, neutrophils and leukocytes were associated with severe and fatal cases of COVID-19." (PMID 34185801, 2021). "Four out of five blood biomarkers associated with an unfavorable COVID-19 disease course (C-reactive protein (CRP), ferritin, lactate dehydrogenase (LDH), and lymphocyte count) were slightly more disadvantageous in the SoC group." (PMID 34045486, 2021). "Analyses did not identify dementia as a risk factor for mortality even though Alzheimer’s disease, a main cause of dementia, is a neuroinflammatory condition that causes elevated levels of c-reactive protein and cytokines commonly related to COVID-19." (PMID 34862487, 2021). "Several risk factors contributing to the progression of COVID-19 were identified, including age, maximum body temperature at admission, respiratory failure, albumin level, and C-reactive protein (CRP)." (PMID 34673806, 2021). "Accordingly, several molecular measurements associated with systemic inflammation, namely, CRP, D-dimers, ferritin, and IL-6 were elevated in plasma from COVID-19 patients in our cohort." (PMID 35095880, 2021). "Nevertheless, our results confirmed the clinical utility of trending CRP and lymphocyte count in monitoring COVID-19 severity and risk stratification." (PMID 33996864, 2021).
COVID-19 (continued). "Pro-inflammatory cytokine interleukin-6 (IL-6) and C-reactive protein (CRP) are biomarkers associated with the COVID-19 progression, severity and mortality." (PMID 34765620, 2021). "Further, a lifestyle score was derived including both physical inactivity, smoking, heavy alcohol consumption, and overweight/obesity, which showed a dose-dependent increased risk of hospitalization for COVID-19 partly explained by C-reactive protein levels." (PMID 34666788, 2021). "Further univariate analysis revealed that the age, sex, cTnI, white blood cells, neutrophils, lymphocytes, C-reactive protein, lactic dehydrogenase, and history of hypertension and diabetes were significantly associated with the clinical severity of COVID-19." (PMID 33909683, 2021). "The CRP level, especially at early hospitalization, has been associated with the extension of COVID-19-induced lung injury and disease progression, and death." (PMID 34150832, 2021). "Plasma CRP levels at hospital admission and 14-day all-cause mortality were assessed in geriatric inpatients hospitalized for COVID-19." (PMID 34506514, 2021). "A group of CVD patients with COVID-19 revealed a consistent association between bad progression and serum CRP concentrations." (PMID 34447386, 2021). "In this pilot study, we compare different alignment methods and show that C-reactive protein (CRP) can be used to synchronize individual patient trajectories to the underlying pathophysiology of COVID-19." (PMID 34307391, 2021). "Clinically, inflammatory markers, such as C-reactive protein, procalcitonin, D-dimer, and ferritin, were increased in COVID-19 patients and associated with a poor prognosis." (PMID 33777042, 2021). "Empirical prescribing of IV antibiotics in hospitalized COVID-19 patients is associated with clinical severity markers like higher qSOFA, fever, older age and raised CRP." (PMID 34223144, 2021). "In the MHD specific COVID-19 study, the mortality rate has been reported to be associated with high CRP levels." (PMID 33446135, 2021). "On the other hand, data obtained in this study also underline the association between COVID-19 and elevation of inflammatory (CRP and ferritin), coagulation (D-dimer), and tissue injury biomarkers (LDH), consistent with recent published studies." (PMID 33718411, 2021). "On the one hand, IL-6 binds to membrane IL-6 receptor (IL-6R) and induces the production of acute-phase proteins such as CRP and fibrinogen, biomarkers associated with poor COVID-19 outcomes." (PMID 34276355, 2021). "The proinflammatory cytokine IL-6 is one of the hallmark cytokines upregulated during severe COVID-19 and represents a predictive marker for the need of mechanical ventilation in accordance with CRP levels." (PMID 34659259, 2021). "They found residual elevation of CRP, D-dimer, and ferritin associating post-COVID-19 related symptoms despite the heterogeneity of their data." (PMID 34777873, 2021). "In univariate analysis, progression to severe COVID-19 was associated with clinical factors (diabetes, obesity, and lung involvement on admission) and levels of biomarkers, including 15 cytokines, CRP, and lymphocytes." (PMID 34386533, 2021). "In a prospective cohort study of 5279 patients in New York with COVID-19, a CRP >200 mg/l had a stronger association with critical illness than age or comorbidities (OR: 5.1; 95% CI 2.8 to 9.2)." (PMID 34567235, 2021). "The association between CRP levels and COVID-19 prognosis has been the subject of some previous studies." (PMID 34506514, 2021). "The top-weighted features IL-6 (R = 0.55), PCT (R = 0.55), CRP (R = 0.52), IL-2R (R = 0.45), and Th/Ts (R = 0.23) were consistent with previously reported risk factors intimately associated with poor outcome of COVID-19." (PMID 33602326, 2021). "Among plenty of factors, lymphopenia, elevated level of d-dimer, hs-CTnT and hs-CRP were independently associated with COVID-19 mortality, suggesting multi-organ dysfunction in young adults of severe COVID-19." (PMID 33407543, 2021).